HMX3 (H6 family homeobox 3)
Description:
Transcription factor involved in specification of neuronal cell types and which is required for inner ear and hypothalamus development. Binds to the 5'-CAAGTG-3' core sequence. Controls semicircular canal formation in the inner ear. Also required for hypothalamic/pituitary axis of the CNS (By similarity).
Synonyms: NKX-5.1; NKX5-1; NKX5.1
Tractability: PROTAC: ubiquitination databases record sites on it.
Gene: Protein-coding gene on chromosome 10 (123,135,970 to 123,139,423, forward strand). Ensembl gene ENSG00000188620.
Subcellular location: Nucleus
Subcellular location (Human Protein Atlas): Nucleoplasm; Centriolar satellite
Gene Ontology:
Molecular function: DNA-binding transcription factor activity, RNA polymerase II-specific; RNA polymerase II transcription regulatory region sequence-specific DNA binding; DNA binding; sequence-specific DNA binding
Biological process: regulation of transcription by RNA polymerase II; ear development; regulation of DNA-templated transcription
Cellular component: chromatin; nucleus
Genetic constraint (gnomAD): Loss-of-function variants: 8 observed, 13.42 expected, observed/expected ratio (o/e) 0.6, 90% interval 0.35 to 1.08. The synonymous counts are far from expectation, so gnomAD's model fits this gene poorly and the ratio says little. Missense variants: 526 observed, 403.33 expected, observed/expected ratio (o/e) 1.3, 90% interval 1.21 to 1.4. Synonymous variants: 330 observed, 208.98 expected, observed/expected ratio (o/e) 1.58, 90% interval 1.44 to 1.73.
Homologues: Orthologues: chimpanzee HMX3 (99% identical), dog HMX3 (98% identical), pig HMX3 (98% identical), macaque HMX3 (98% identical), guinea pig HMX3 (97% identical), mouse Hmx3 (96% identical), rat Hmx3 (96% identical), rabbit HMX3 (72% identical), tropical clawed frog hmx3 (65% identical), zebrafish hmx3a (63% identical). Paralogues in human: HMX1 (38% identical), HMX2 (31% identical), HOXA9 (16% identical).
Diseases named in the same sentence as HMX3 in open-access papers:
HMX3 is named in the same sentence as 15 diseases in open-access papers, as found by Europe PMC text mining. Sharing a sentence is not in itself a finding about the gene and the disease. The quoted sentences say what the papers report.
breast carcinoma (2 papers, 2014 to 2017). "Similarly, the other confirmed partner, HMX3, is an activated transcription factor regulator in the HER2 subtype of breast cancer." (PMID 28569207, 2017). "HMX3 has been shown to integrate ESR1 and HER2 receptor tyrosine kinase signaling to promote aromatase expression and hormone resistance in a preclinical model of luminal breast cancer." (PMID 25183703, 2014).
chronic lymphoid leukemia (1 paper, 2020). "Aberrant expression of HMX2 and/or HMX3 was also detected in a few lymphoid cell lines derived from B-cell precursor leukemia, chronic lymphoid leukemia and hairy cell leukemia, also indicating deregulation of these genes in some B-lymphoid malignancies." (PMID 33048949, 2020).
Cirrhosis (1 paper, 2021). A chronic disorder of the liver in which liver tissue becomes scarred and is partially replaced by regenerative nodules and fibrotic tissue resulting in loss of liver function. "In particular, E2 could retard HCC (also NASH and cirrhosis) progression, particularly in both the male gMXs + Dox zebrafish, while 11-KT could promote HCC progression predominantly in male hMX3+Dox zebrafish." (PMID 34943942, 2021).
colorectal cancer (1 paper, 2025). A primary or metastatic malignant neoplasm that affects the colon or rectum. "The positive regulatory effect of USP38 on HMX3 expression indicates that in colorectal cancer, USP38 can influence tumor cell growth by regulating multiple signaling pathways (such as the USP38/HDAC3 signaling axis and the USP38/LSD1 signaling axis)." (PMID 40936898, 2025). "In colorectal cancer, overexpression of USP38 can activate downstream tumor-suppressive signaling pathways by promoting the expression of key regulatory factors such as HMX3 and HDAC3." (PMID 40936898, 2025).
deafness (1 paper, 2013). An inherited or acquired condition characterized by the complete loss of the ability to hear from one or both ears. "Their absence, together with the reduced expression of Hmx3, Hmx2 and Nkx1.2, which are located at the same chromosomal region, causes deafness and vestibular problems both in mice and humans." (PMID 23457544, 2013). "We have previously reported in published abstracts the head bobbing and circling behavior, deafness, failure in semicircular canal formation, mapping of the phenotype and the transgene to chromosome 7 by linkage analysis, and non-complementation with Hmx3 and present the full dataset here." (PMID 23457544, 2013).
liver cancer (1 paper, 2021). An epithelial or non-epithelial malignant neoplasm that arises from the liver. "In this study, we showed a similar sexual dimorphism in the liver cancer progression of hMX3." (PMID 34943942, 2021).
liver steatosis (1 paper, 2021). "As expected, the hMXs + Dox (hMX1 + Dox and hMX3 + Dox) groups at 24 dpf developed palpable liver steatosis, whereas control groups showed no or few fat accumulations." (PMID 34943942, 2021).
myelodysplastic syndrome (1 paper, 2021). A clonal hematopoietic disorder characterized by dysplasia and ineffective hematopoiesis in one or more of the hematopoietic cell lines. "However, HMX2 and HMX3 are aberrantly expressed in AML and the activity of HMX1 was detected in subsets of myelodysplastic syndrome (MDS) patients." (PMID 33921702, 2021).
sensorineural hearing loss (1 paper, 2019). "In humans, HMX3 and HMX2 are located together, close to FGFR4, on chromosome 10; hemizygous microdeletions that remove all three genes are thought to be causative for syndromes characterised by inner ear morphological anomalies, vestibular dysfunction and sensorineural hearing loss." (PMID 31022185, 2019).
Vertigo (1 paper, 2023). An abnormal sensation of spinning while the body is actually stationary. "Two other genes, HMX3 and LAMA2, were identified to have rare missense variants in children with vertigo and are strongly expressed in human vestibular tissues." (PMID 37107589, 2023). "Although less well-described, human studies also suggest HMX3 involvement in vertigo." (PMID 37107589, 2023). "The knockout of HMX3 in mice led to abnormal circling behavior and severe structural defects in the inner ear vestibule; however, prior to this work, there was no strong evidence of vertigo-causal HMX3 variants in humans." (PMID 37107589, 2023).
cancer (2 papers, 2017 to 2021). A tumor composed of atypical neoplastic, often pleomorphic cells that invade other tissues. "As hMX3 + Dox fish showed marked activation via inflammation (or oncogenesis) and accelerated NASH, we analyzed whether the livers of hMX3+Dox group were inclined to cancer progression from the beginning." (PMID 34943942, 2021).
tumor (1 paper, 2025). "Subsequent immunoprecipitation and deubiquitination experiments demonstrated that the inhibitory effect of HMX3 on tumor cells is USP38-dependent: USP38’s deubiquitinating activity enhances HMX3 protein stability, thus strengthening its tumor-suppressive effect." (PMID 40936898, 2025).
HMX3 also shares sentences with these, for which no sentence is quoted: acute myeloid leukemia (1 paper); esophageal squamous cell carcinoma (1); hairy cell leukemia (1).